GNLY (granulysin)
Diseases named in the same sentence as GNLY in open-access papers (continued):
Sharing a sentence is not in itself a finding about the gene and the disease.
alopecia areata (2 papers, 2024). Loss of scalp and body hair involving microscopically inflammatory patchy areas. "A significantly higher GNLY level was found in the blood of patients with alopecia areata, which correlated positively with the extent of hair loss, suggesting that the GNLY serum level could be a biological marker of disease activity." (PMID 39020008, 2024). "Similar to alopecia areata patients, the serum granulysin level in this study was also statistically significantly higher in the patient group than in the control group." (PMID 38775500, 2024). "GNLY is highly expressed in numerous immune-mediated skin diseases such as lichen planus, alopecia areata and psoriasis." (PMID 39020008, 2024).
ankylosing spondylitis (2 papers, 2014 to 2021). An autoimmune chronic inflammatory disorder characterized by inflammation in the vertebral joints of the spine and sacroiliac joints. "Nonbeneficial effects of anti-TNF immunotherapy in chronic inflammatory diseases (as rheumatoid arthritis and ankylosing spondylitis) associated with reactivation of Mycobacterium infection may be attributed to the depletion of the cytolytic CD8+perforin+/granulysin+ CTL population by Infliximab." (PMID 25140115, 2014).
breast carcinoma (2 papers, 2022 to 2024). "Another study on primary untreated breast cancer patients revealed that high levels of GNLY mRNA predict a low risk of local recurrence but a high risk of distant metastasis." (PMID 39643914, 2024).
B‐cell lymphoma (2 papers, 2018 to 2020). "Increased levels of activation and granulysin secretion were also observed when Vδ2+γδ T cells were cultured with the human B‐cell lymphoma line Daudi." (PMID 32794189, 2020).
Cirrhosis (2 papers, 2007 to 2022). A chronic disorder of the liver in which liver tissue becomes scarred and is partially replaced by regenerative nodules and fibrotic tissue resulting in loss of liver function. "Seven DEGs (TYMP, TYROBP, CD14, TGFBI, LILRA2, GNLY, and GZMB) were common to HCC, cirrhosis, and CHB when compared to healthy controls." (PMID 35265561, 2022).
coinfection (2 papers, 2019 to 2020). The simultaneous infection of a host by multiple pathogen species. "Granulysin may act synergistically with perforin and IFN-γ by the significant correlation of granulysin with granzyme-B and perforin levels in TB or HIV/TB coinfection, and their effector mechanisms could contribute to control TB." (PMID 32823923, 2020). "Before anti-TB treatment, the in vitro levels of granulysin, perforin, granzyme-B and IFN-γ released from PBMCs of active TB or HIV/TB coinfection patients after PPD and H37Ra stimulation were analyzed in comparison with those of HIV+HAART−, HIV+HAART+ and healthy individuals (HC) as controls." (PMID 32823923, 2020). "Upon stimulation, the non-significantly higher median levels in TB than HIV/TB coinfection were observed in granulysin, perforin and granzyme-B." (PMID 32823923, 2020).
cutaneous leishmaniasis (2 papers, 2021 to 2024). Leishmaniasis affecting the skin. "Studies have shown that localized skin inflammation in cutaneous leishmaniasis leads to a chronic systemic IFN-γ signature, with increased expression of cytotoxic markers GZMB, Pore-forming protein 1(PRF1), and GNLY." (PMID 39342024, 2024). "In a recent transcriptomic study of skin samples of cutaneous leishmaniasis patients, delayed or absence of cure was correlated with higher expression of gene sets related to the cytolytic pathway, including mRNAs for granzyme (GZMB), perforin (PRF1), and granulysin (GNLY)." (PMID 34178725, 2021).
halo nevus (2 papers, 2024). A benign melanocytic nevus with a halo appearance. "In halo nevus, however, we observed an increased expression of GNLY+ cells in the papillary dermis." (PMID 39020008, 2024). "In halo nevus, GNLY+ cells were found in the epidermis and dermis surrounding nests of nevus cells." (PMID 39020008, 2024). "In halo nevus, dense infiltrates of CD8+ GNLY+ cells were accumulated in the perilesional epidermis and dermis, whereas no double-positive cells were detected in healthy skin." (PMID 39020008, 2024).
Hypertension (2 papers, 2023 to 2026). The presence of chronic increased pressure in the systemic arterial system. "ISLR2 was found to be associated with hypertension, and SFTPB displayed an association with Granulysin." (PMID 37735436, 2023).
polymyositis (2 papers, 2022 to 2025). A rare idiopathic inflammatory myopathy characterized by symmetric proximal muscle weakness and elevated muscle enzymes. "The upregulation of granulysin (GNLY), encoding for the cytosolic protein granulysin (expressed in cytotoxic T cells and natural killer cells, and previously associated with polymyositis, and chemerin (RARRES2), a leukocyte chemoattractant, may be related to the inflammation process." (PMID 40841884, 2025).
prostate carcinoma (2 papers, 2022). A carcinoma that arises from epithelial cells of the prostate gland. "For study #1, we expect that the combined use of our three phytoncides of interest and VR will improve NK cell numbers and activity and blood levels of perforin and granulysin in patients with breast or prostate cancer." (PMID 35564767, 2022). "Likewise, we determined that using these treatments in combination with anti-TIGIT increases and maintains the expression of some factors such as NKp46 and secretion of granzyme A, granzyme B, perforin, and granulysin which may regulate cytotoxicity against DU145 prostate cancer cells." (PMID 35465350, 2022). "Finally, the disruption of the IL6R/STAT-3 axis in prostate cancer cells and the blocking of TIGIT on NK-92 were observed to increase the cytotoxicity of NK-92 cells against DU145 cells through an increase in sFasL, granzyme A, granzyme B, and granulysin." (PMID 35465350, 2022).
pulmonary veno-occlusive disease (2 papers, 2018 to 2020). "Further, hypermethylation of CpG islands at SOD2 locus was identified in patients with IPAH117 and also at granulysin (GNLY) locus in patients with pulmonary veno-occlusive disease, but not in IPAH or heritable PAH62." (PMID 33150154, 2020).
sarcoma (2 papers, 2019 to 2024). A usually aggressive malignant neoplasm of the soft tissue or bone. "In parallel, we observed an increased release of granzymes, perforin, and granulysin from NK cells upon co-culture with MeV-infected A673 human sarcoma cells." (PMID 31795974, 2019). "Furthermore, we observed an increased release of granzymes, perforin, and granulysin from NK cells upon co-culture with MeV-infected A673 human sarcoma cells." (PMID 31795974, 2019). "T‐cells in the sarcoma microenvironment exhibited elevated levels of cytotoxicity (GZMB, GNLY and KLRD1), exhaustion (HAVCR2, CD38, CD160, CXCL13 and CX3CR1), and inflammation (IL33, PPARG, IL6R and SOCS3), suggesting an activated but exhausted phenotype." (PMID 39658531, 2024).
Achalasia (1 paper, 2023). A disorder of esophageal motility characterized by the inability of the lower esophageal sphincter to relax during swallowing and by inadequate or lacking peristalsis in the lower half of the body of the esophagus. "We found the proportions of circulating lymphocytes were similar between achalasia and controls except for the increased populations of GNLY+ CD8+ T cells (Tc8), CD27+ B cells (B2), and plasma in achalasia." (PMID 37542039, 2023). "Next, achalasia-associated transcriptional changes of lymphocytes in peripheral blood were analyzed, especially for GNLY+ CD8+ T cells, CD27+ B cells, and plasma, which were proportionally increased in achalasia." (PMID 37542039, 2023). "Analysis of differentially expressed transcripts of lymphocytes in achalasia showed that TRM, GZMK+ CD8+ T cells (Tc2), and GNLY+ CD8+ T cells had more DEGs than other lymphocytes." (PMID 37542039, 2023). "However, several cytotoxic enzymes and inflammatory cytokines, including GZMA, GZMB, GZMK, GNLY, and TNF were downregulated in TRM in achalasia, consistent with a previous study of TRM in MS42." (PMID 37542039, 2023).
acne (1 paper, 2024). An inflammatory process of the sebaceous glands which is characterized by comedones, nodules, papules and/or pustules on the skin. "A reduction of acne severity after 12 weeks of topical treatment was also reported for a combination of 20 granulysin-derived peptides (GDP 20) in a study involving 30 AV patients." (PMID 39744637, 2024). "Nonetheless, several AMPs share specific amino acid motifs with human endogenous AMPs, including hBDs, LL-37, dermcidin, RNAse 7, or granulysin, which may explain their anti-acne properties." (PMID 39744637, 2024). "T cells in early and late acne lesions imply granulysin’s importance for acne pathogenesis." (PMID 39744637, 2024). "While dermcidin, granulysin (GNLY), RANTES (CCL5), perforin, CXCL9, and two neuropeptides (substance P and chromogranin B) remained unaffected either in untreated acne patients as well as by isotretinoin treatment." (PMID 39744637, 2024).
anaplastic large cell lymphoma (1 paper, 2018). Anaplastic large cell lymphoma (ALCL) is a rare and aggressive peripheral T-cell non-Hodgkin lymphoma, belonging to the group of CD30-positive lymphoproliferative disorders, which affects lymph nodes and extranodal sites. "Furthermore, expression of granulysin was observed in rare cases of T cell lymphomas with a cytotoxic phenotype (i.e. ALK-negative anaplastic large cell lymphoma (26%), enteropathy-associated T cell lymphoma (12%) and peripheral T cell lymphoma, NOS (4%))." (PMID 30151671, 2018).
antiphospholipid antibody syndrome (1 paper, 2022). "The authors aimed to evaluate whether granulysin is associated with the antiphospholipid antibody syndrome and whether heparin changes the granulysin levels." (PMID 35444491, 2022).
atherosclerosis (1 paper, 2025). A disease characterized by the build-up of fatty material and calcium deposition in the arterial wall resulting in partial or complete occlusion of the arterial lumen. "Thus, KGs of NK cells for hawthorn's effects on the PVAT microenvironment of atherosclerosis were JUN, CXCR4, CD36, GNLY, and FABP4." (PMID 40824771, 2025).
bladder cancer (1 paper, 2023). "Consistently, the current study also showed that GNLY is specifically expressed in bladder cancer T cells." (PMID 37069207, 2023).
bladder tumors (1 paper, 2023). "From the identified signature gene set, MDGA2, GNLY, DLX1, and DSC1 were selected for expression analysis in bladder tumors and matching blood samples of 10 BLCA patients." (PMID 37876438, 2023).
bladder urothelial carcinoma (1 paper, 2023). "Additionally, GNLY, HOXB7, MRPL33, and PRDM16 were upregulated in bladder urothelial carcinoma, colon adenocarcinoma, lung adenocarcinoma, and rectum adenocarcinoma based on the results of eRic validation." (PMID 37534217, 2023).
chordoma (1 paper, 2023). Chordomas are rare malignant tumors arising from embryonic remnants of the notochord in axial skeleton. "The examination of NKT and NK cells in chordoma revealed their elevated cytotoxicity, which was distinguished by the presence of PRF1, GZMB and GNLY." (PMID 37784253, 2023).
chronic lymphocytic leukemia (1 paper, 2020). "Therapeutic strategies based on granulysin analogues have been studied, showing in vitro activity in cell lines and primary chronic lymphocytic leukemia (CLL) and multiple myeloma (MM) cells." (PMID 32466293, 2020).
colorectal adenocarcinoma (1 paper, 2023). The most common type of colorectal carcinoma. "The DElncRNA AP002498.1 and the LINC01871/miR‐4644 and miR‐185‐5p/GNLY axes were identified as being closely associated with distant metastasis and could represent independent prognostic biomarkers or therapeutic targets in colorectal adenocarcinoma." (PMID 38083905, 2023).
flu (1 paper, 2021). "We noted increased expression of genes related to cytotoxicity, activation and inflammation—such as GZMB, GNLY, TYROBP, HOPX, and CCL5—in the CD8 EMRA-like two cluster that was expanded in CAP-flu." (PMID 34424199, 2021).
gastric carcinoma (1 paper, 2023). A carcinoma that arises from epithelial cells of the stomach. "Elevated granulysin concentrations have been detected in gastric carcinoma patients with less severe disease than those with advanced stage gastric carcinomas." (PMID 37153585, 2023).
hematoma (1 paper, 2025). A hematoma is a collection of blood from a vascular structure into an extravascular space. "We found that the CD8_GNLY subcluster was increased in the peripheral blood and hematoma of ICH patients, along with high expression of effector genes such as GNLY, GZMB and GZMH." (PMID 41238793, 2025).
HIV-1 infection (1 paper, 2025). The type species of lentivirus and the etiologic agent of acquired immunodeficiency syndrome (AIDS). "Furthermore, it has been reported that both CD4+ cytotoxic T lymphocytes (CTLs) and CD8+ CTLs expressing GNLY, GZMB, PRF proteins exhibit antimicrobial activity against intracellular bacteria and in HIV-1 infection." (PMID 40264781, 2025).
Immunodeficiency (1 paper, 2025). Failure of the immune system to protect the body adequately from infection, due to the absence or insufficiency of some component process or substance. "Patients with severe immunodeficiency have been reported to have very low GNLY serum levels." (PMID 39851522, 2025).
latent infection (1 paper, 2016). "First, the present data may reflect sequestration of GNLY-producing cells: Lymphocytes with high GNLY expression accumulate at the sites of latent infection." (PMID 27756230, 2016).
Listeria monocytogenes infection (1 paper, 2024). "show that human decidual NK cells, with higher expression of granulysin than peripheral NK cells, can defense Listeria monocytogenes infection and protect fetus by infusion of granulysin into placental trophoblast cells via nanotubes and removing the intracellular pathogen." (PMID 38545107, 2024).
liver cancer (1 paper, 2023). An epithelial or non-epithelial malignant neoplasm that arises from the liver. "Large proportions of memory CD8 T cells (CD8+GZMK+, and CD8+IL7R+) as well as a group of cytotoxic CD8 T cells (CD8+GNLY+) were enriched in liver cancers with low clonality." (PMID 36980203, 2023). "Cytotoxic CD8 T cells (CD8+GNLY+) were found to be a major source of cytokines and chemokines secretion in liver cancers with low clonality, while proliferative pre-exhaustion T cells (CD8+MKI67+CXCL13+) were the main source in liver cancers with high clonality." (PMID 36980203, 2023).
liver cirrhosis (1 paper, 2022). "When compared to healthy controls, only 7 DEGs, including 6 up-DEGs (TYMP, TYROBP, TGFBI, LILRA2, GNLY, and GZMB) and 1 down-DEG (CD14) were common to CHB, liver cirrhosis, and HCC." (PMID 35265561, 2022).
lupus nephritis (1 paper, 2025). Glomerulonephritis in the context of systemic lupus erythematosus. "Furthermore, transcriptomic single cell analysis has revealed the presence of subsets of tissue resident memory CD8+ T cells and cytotoxic CD8+ T cells expressing perforin, granzyme B and granulysin in renal tissue from patients with lupus nephritis." (PMID 39719886, 2025).
lymphoid neoplasm (1 paper, 2018). A neoplasm composed of a lymphocytic cell population which is usually malignant (clonal) by molecular genetic and/or immunophenotypic analysis. "Among lymphoid neoplasms, the highest expression of granulysin (71%) was found in extranodal NK/T cell lymphomas of nasal type (ENKTL)." (PMID 30151671, 2018).
lymphoma (1 paper, 2018). A malignant (clonal) proliferation of B- lymphocytes or T- lymphocytes which involves the lymph nodes, bone marrow and/or extranodal sites. "The findings led to suggest granulysin as a potential diagnostic and prognostic marker for these lymphoma types." (PMID 30151671, 2018). "In conclusion, our study suggests granulysin as an additional molecule for cytotoxic and NK/T cells as well as a reliable diagnostic marker for NK/T cell-derived lymphoma subtypes and useful for those ENKTLs that lack expression of one or more of the commonly used cytotoxic markers." (PMID 30151671, 2018). "Abnormal serum levels of granulysin in lymphomas with NK and cytotoxic phenotype have been shown to correlate with tumour progression." (PMID 30151671, 2018). "In this study, we investigated the expression pattern of granulysin in routine sections of normal and reactive lymphoid tissues as well as in a large series of lymphomas." (PMID 30151671, 2018). "In the current study, we show that granulysin is expressed in cytotoxic/NK lymphocytes and in subsets of NK/T cell derived lymphomas." (PMID 30151671, 2018). "Our results showing granulysin expression in a small proportion of other lymphomas with cytotoxic phenotypes, i.e. ALK-negative ALCL, EATL and PTCL NOS support previous observations of granulysin positivity in systemic ALCL of childhood, in mycosis fungoides (MF) and Sézary syndrome." (PMID 30151671, 2018). "Although we found granulysin expression in the majority of ENKTCL cases, further experiments with NK and cytotoxic T cell lines are required to demonstrate granulysin as a cytotoxic marker of NK cells and derived lymphomas and to correlate with cell of origin (NK versus T cell)." (PMID 30151671, 2018).
mastitis (1 paper, 2018). Inflammation of breast tissue during lactation or postpartum due to an obstructed duct or infection. "As shown by flow cytometry, there were a heightened number of CD45 positive HM cells with co-expression of granzymes, granulysin and perforin from a participant with mastitis." (PMID 30181507, 2018).
metastatic melanoma (1 paper, 2023). A melanoma that has spread from its primary site to another anatomic site. "GNLY was previously revealed to be also linked to the cytotoxicity and characteristic of effector memory T cells in metastatic melanoma patients." (PMID 37069207, 2023).
Miscarriage (1 paper, 2022). A pregnancy that ends at a stage in which the fetus is incapable of surviving on its own, defined as the spontaneous loss of a fetus before the 22th week of pregnancy. "Based on these findings, granulysin can be used for an evaluation of immunity and it may be involved in miscarriage." (PMID 35444491, 2022). "Moreover, NKT cells produce granulysin, which has been reported to induce miscarriage." (PMID 35444491, 2022).
myxoma (1 paper, 2024). A benign soft tissue neoplasm characterized by the presence of spindle and stellate cells, lobulated growth pattern, and myxoid stroma formation. "Lymphocytes within myxoma tissues exhibit elevated expression of certain genes associated with extracellular matrix adhesion, while their capacity to express cytotoxic molecules such as GNLY, GZMB, and NKG7 is diminished." (PMID 39090109, 2024).
nevus (1 paper, 2024). Nevus (or naevus, plural nevi or naevi, from nævus, Latin for "birthmark") is the medical term for sharply circumscribed[1] and chronic lesions of the skin or mucosa. "In halo nevus, we detected a dense dermal and epidermal infiltrate of CD8+ GNLY+ cells in close contact with nevus cells." (PMID 39020008, 2024).
NK/T cell lymphomas (1 paper, 2018). "Finally, it should be mentioned that granulysin may represent a potential therapeutic target for NK/T cell lymphomas that are characterised by a poor prognosis." (PMID 30151671, 2018).
non-small cell lung carcinoma (1 paper, 2024). A group of at least three distinct histological types of lung cancer, including non-small cell squamous cell carcinoma, adenocarcinoma, and large cell carcinoma. "EVs secreted by NK cells carry signature NK markers and cytotoxic proteins, such as granzyme A and B, granulysin, and perforin, which mediate antitumor effects against solid tumors, such as neuroblastoma, breast cancer, and non-small cell lung cancer (NSCLC)." (PMID 39724442, 2024).
Obesity (1 paper, 2017). Accumulation of substantial excess body fat. "Proteins we identified as potentially linked to obesity for the first time included the RET proto-oncogene (granulysin)." (PMID 29234017, 2017).